GAL (galanin and GMAP prepropeptide)
Diseases named in the same sentence as GAL in open-access papers (continued):
Sharing a sentence is not in itself a finding about the gene and the disease.
Insulin resistance (7 papers, 2015 to 2025). Increased resistance towards insulin, that is, diminished effectiveness of insulin in reducing blood glucose levels. "Typically, the increase in visceral fat has been verified to further boost insulin resistance, while MetS is probably induced by insulin resistance caused by the association between GAL-3BP levels and visceral adiposity." (PMID 34858323, 2021). "Next, GAL-GalR1 system in brain can suppress sympathetic firing in a dose-dependent way, which is implicated in alleviation of insulin resistance." (PMID 27127795, 2016). "Immune biomarkers such as PGE and the NLRP-3 inflammasome, oxidative stress pathways, GAL-GAL-R1, and metabolic pathways including insulin resistance and PAI1 are new drug targets to prevent and treat long COVID and its physio-affective symptoms." (PMID 40048451, 2025). "For instance, GAL ameliorates insulin resistance and improves glucose metabolism by activating the trafficking of glucose transporter 4 and glucose uptake in the skeletal muscle and adipose tissue." (PMID 33925193, 2021). "In healthy and obese children, the relationships between GAL serum levels and metabolic parameters (insulin, glucose, lipids, homeostasis model assessment-insulin resistance, leptin) have been studied." (PMID 33802616, 2021). "Thus, in obese children, serum levels of GAL are positively correlated with triglycerides and insulin resistance." (PMID 33802616, 2021). "Compared to healthy individuals, serum levels of both leptin and GAL were higher in obese children and the levels of GAL were positively correlated with the levels of fasting insulin, homeostasis model assessment-insulin resistance, triglycerides, and fasting glucose." (PMID 33802616, 2021). "Thus, our findings showing the coexistence of increased GAL levels and insulin resistance are compatible with the existence of a state of GAL resistance in obese subjects." (PMID 27550417, 2016). "The present findings showed that the beneficial effect of central M617 on insulin sensitivity was same as that of central GAL in adipose tissues, suggesting that the mitigatory effect of central GAL on insulin resistance is mainly mediated by activation of GalR1." (PMID 27127795, 2016). "GAL appears to have a different role in the scenario of insulin resistance." (PMID 27550417, 2016). "The increase in GAL could be due to the appearance of GAL tissue resistance or might be a compensatory mechanism against the insulin sensitivity increase observed in obese subjects suffering from insulin resistance." (PMID 33802616, 2021). "The HAMD/HAMA/FF scores showed significant correlations with several factors such as PGE, CRP, GAL, GALR1, insulin resistance, and PAI1 levels." (PMID 40048451, 2025). "Moreover, it was suggested that the serum insulin level is a predictor of the serum level of GAL and that the high serum level of GAL observed could be associated with the increase in body weight reported in obese (non-diabetic) individuals and to insulin resistance." (PMID 33802616, 2021).
colon carcinoma (6 papers, 2018 to 2022). "The GAL mRNA level was observed to be elevated and was significantly associated with tumor stages in colon cancer, while it was also indicated as a tumor suppressor correlated with low disease-free survival in head and neck squamous cell carcinoma." (PMID 32724813, 2020). "Stage/tumor size has been related to the level of GAL mRNA in colon cancer: the higher the GAL expression, the shorter the disease-free survival." (PMID 35954419, 2022). "The galaninergic system is involved in colon cancer; thus, for example, the siRNA-mediated silencing of the GAL gene reduced both invasive and proliferative potential in CRC cells." (PMID 35954419, 2022). "The stage and tumor size in colon cancer have been related to the GAL mRNA level: the higher the GAL expression, the shorter the disease-free survival." (PMID 35954419, 2022). "The GAL level in healthy patients was 25.6 ± 14.5 ng/ml, while in those with colon cancer, it was significantly higher (41.4 ± 19.0 ng/ml)." (PMID 33552060, 2020). "In colon cancers, GAL mRNA levels correlated with tumor size and stage, for which a significant correlation between high GAL expression and shorter disease-free survival in colon cancer patients was observed." (PMID 32265844, 2020). "In the rat model, GAL injection in gastric or colon cancer resulted in a significant inhibition of carcinogenicity." (PMID 33552060, 2020). "Finally, GAL decreased the incidence of colon tumors in rats and it seems that this effect was due to the inhibitory action exerted by GAL on cancer cell proliferative mechanisms." (PMID 35954419, 2022). "Recent studies identified that overexpression of GAL in colon cancer and silencing of GAL could result apoptosis and enhanced chemotherapy effects." (PMID 34535962, 2021). "Recent research suggests that GAL may be considered a biomarker of colon cancer." (PMID 33552060, 2020). "CRC tissues showed higher GAL levels than the corresponding non-tumor tissues, and human colon cancer cell lines (LOVO, HCT15, SW480, SW620) showed higher levels of GAL than those found in non-colon cancer cell lines." (PMID 35954419, 2022). "In studies aimed at determining serum GAL levels in patients with colon cancer compared to serum from non-cancerous controls revealed a significant increase in its level in the case of colon adenocarcinoma." (PMID 33552060, 2020). "It was reported that in rats with gastric carcinogenesis induced by N-methyl-N′-nitro-N-nitrosoguanidine, prolonged administration of GAL significantly decreased the incidence of gastric and colon cancers without influence on the histological types of cancers." (PMID 30373200, 2018). "GAL has also been detected in a variety of non-neuroendocrine human tumors of different origin, including glioblastoma and other brain tumors, melanoma, head and neck squamous cell carcinoma (HNSCC), basal cell carcinoma, colon cancer and embryonic carcinoma." (PMID 32265844, 2020).
colorectal cancer (5 papers, 2020 to 2023). A primary or metastatic malignant neoplasm that affects the colon or rectum. "However, it was also reported that high expression of GAL was associated with suppression of cell proliferation and then promoted tumor cell apoptosis in colorectal cancer." (PMID 35751103, 2022). "For example, colorectal cancer patients exhibited increased levels of GAL in serum and colon tissues, whereas the silencing of GAL and GAL1-R induced apoptosis and enhanced the effect of chemotherapy." (PMID 37443714, 2023). "In our previous studies, the GAL immunoexpression was compared in colorectal cancer (CRC) tissue and the adjacent parts of the large intestine wall including myenteric and submucosal plexuses." (PMID 36551197, 2022). "In previous studies, the GAL protein expression was determined in serum and tissue of colorectal cancer (CRC) patients as well as the parts of the colon wall including myenteric and submucosal plexuses." (PMID 36551197, 2022). "Through stabilizing GLUT1, the LncRNA GAL enhances colorectal cancer liver metastasis." (PMID 37842058, 2023). "Moreover, the overexpression of GAL was reported close to relapse, micro-metastases, and recurrence in colorectal cancer and eventually resulted in poor prognosis." (PMID 35751103, 2022). "However, Godlewski and Pidsudko noted a decrease in GAL levels in colorectal carcinoma tissues compared to the control group, as well as an increase in GAL presence within MP neurons." (PMID 33552060, 2020). "GAL and its receptor GalR1 might have novel potential for overcoming chemotherapy resistance though mitogen-activated protein kinase signaling and the insulin signaling pathway in colorectal cancer." (PMID 35751103, 2022).
COVID-19 (5 papers, 2020 to 2023). A disease caused by infection with severe acute respiratory syndrome coronavirus 2. "Further results deriving from our research are the demonstration of a macrophage sub-population shift, and association between loss of alveolar GAL-3 macrophages and persistence of viral sequences Spike-1 as a crucial event in lethal COVID-19 lung disease." (PMID 37686069, 2023).
gastric cancer (5 papers, 2018 to 2023). A primary or metastatic malignant neoplasm involving the stomach. "In gastric cancer, however, studies associate GAL with anti-tumour effects, as the downregulation of GAL correlates with metastasis and cancer progression." (PMID 37443714, 2023). "In vitro and in vivo experiments using human gastric cancer cell lines have been performed to study the antitumor action of a triple treatment with GAL, serotonin and octreotide (an octapeptide that mimics the actions mediated by somatostatin)." (PMID 35954419, 2022). "In patients suffering from gastric cancer, lower levels of GAL were observed in pre-operative samples (and in plasma) when compared with those found in post-operative samples obtained from the same patients or from samples of healthy donors." (PMID 35954419, 2022). "GAL downregulation favored tumor development in gastric cancer, which was due to an epigenetic inactivation, since the hypermethylation of GAL impaired its tumor-suppressive action." (PMID 35954419, 2022). "Moreover, it is reported that the hypermethylation of GAL promotor regions epigenetically silences GAL in gastric cancer cells, negatively correlating with tumour size and tumour-suppressive properties." (PMID 37443714, 2023). "In addition, the hypermethylation of GAL impaired its tumor suppressor action in gastric cancer, and the exogenous GAL expression in silenced cells promoted a decrease in phosphorylated Akt expression and apoptosis." (PMID 35954419, 2022). "Moreover, the levels of GAL/GAL1R were lower in gastric cancer tissues compared with those found in adjacent regions; however, the GAL2R/GAL3R levels did not change." (PMID 35954419, 2022). "The low level of GAL could be used as a biomarker in gastric cancer and, importantly, in these patients (pre-operative samples), the GAL protein/mRNA levels have been related to tumor size, tumor node metastasis stage and lymph node metastasis." (PMID 35954419, 2022). "Finally, GAL decreased the proliferation of human gastric cancer cells in vitro." (PMID 35954419, 2022). "GAL and its receptors might contribute to the development of gastric cancer." (PMID 35751103, 2022). "Human gastric cancer cells (AGS, KATOIII, SNU-638, SNU-601, SNU-1) showed a low endogenous GAL expression, which was restored with a demethylating agent (5-aza-2′-deoxycytidine)." (PMID 35954419, 2022).
Alzheimer disease (4 papers, 2016 to 2022). A progressive, neurodegenerative disease characterized by loss of function and death of nerve cells in several areas of the brain leading to loss of cognitive function such as memory and language. "An increase in the GAL gene expression and galanin levels has already been found in some diseases, among which Alzheimer’s disease is again at the forefront." (PMID 32366041, 2020). "Here, it was found that patients treated with donepezil as well as with GAL showed relevant improvement in Alzheimer's Disease Assessment Scale-cognitive subscale (ADAS-cog) compared to the placebo group, but not in the Mini Mental State Examination (MMSE)." (PMID 27110749, 2016). "GAL agonists or antagonists (e.g., galantide, M35, M40, C7) have been used for the treatment of several disorders: GAL antagonists have been administered for the treatment of food intake disorders and Alzheimer’s disease, whereas GAL agonists have been used for the treatment of chronic pain." (PMID 35954419, 2022).
endometritis (4 papers, 2021 to 2022). An acute or chronic, usually bacterial infectious process affecting the endometrium. "Endometritis-evoked emergence of VAChT+/GAL+ and VAChT-/GAL+ populations may suggest an increasing demand to upregulate this valuable neurotransmitter in order to benefit from its favorable properties." (PMID 35804576, 2022). "The current report presents the action of endometritis on the GALR1 and GALR2 protein expression in the myometrium, and the importance of GAL, GALR1, and GALR2 in the contractile activity of a pig uterus with inflammation." (PMID 34203944, 2021). "In the DRGs of gilts suffering from endometritis, the numbers of uterine perikarya immunopositive to NA, NPY, GAL, or vasoactive intestinal peptide were increased." (PMID 34203944, 2021).
epilepsy (4 papers, 2019 to 2025). A brain disorder characterized by episodes of abnormally increased neuronal discharge resulting in transient episodes of sensory or motor neurological dysfunction, or psychic dysfunction. "At several epilepsy-related genes, like HDAC11, SPP1, GAL, DRD1 and SV2C, significant differential methylation and differential gene expression coincided." (PMID 31887157, 2019).
Fabry disease (4 papers, 2018 to 2025). Fabry disease (FD) is a progressive, inherited, multisystemic lysosomal storage disease characterized by specific neurological, cutaneous, renal, cardiovascular, cochleo-vestibular and cerebrovascular manifestations. "Fabry disease (FD) is a life-threatening X-linked lysosomal storage disorder caused by α-galactosidase A (α-GAL) deficiency." (PMID 30328411, 2018). "The diagnosis of Fabry disease is generally suspected on the basis of a low a-GAL enzyme activity, which can be measured in plasma, leukocytes or dried blood spot (DBS)." (PMID 32227072, 2020). "Fabry disease is a rare X-linked lysosomal storage disorder caused by mutations in the GLA gene (position Xq22), which encodes the a-galactosidase A (a-GAL) enzyme." (PMID 32227072, 2020). "The finding showed that neither clinical phenotype, GAL activity, nor lyso-Gb3 levels showed any difference in relation to XCI.In summary, the authors demonstrated that in women with Fabry disease, XCI patterns have limited use in understanding disease severity." (PMID 41150803, 2025).
head and neck squamous cell carcinoma (4 papers, 2020 to 2022). A squamous cell carcinoma that arises from any of the following anatomic sites: lip and oral cavity, nasal cavity, paranasal sinuses, pharynx, larynx, and salivary glands. "GAL methylation status may be an important marker for predicting clinical prognosis in patients who are with head and neck squamous cell carcinoma." (PMID 35464849, 2022).
hepatocellular carcinoma (4 papers, 2013 to 2023). A malignant tumor that arises from hepatocytes. "Overexpression of OPTN increases mitophagy and is related to worse prognosis in hepatocellular carcinoma (HCC) patients.The expression of GAL up-regulated in neuroblastic cancers." (PMID 36419120, 2022). "The addition of GAL increased the specificity of dendrimers against hepatocellular carcinoma cells, by using asialoglycoprotein as a molecular target." (PMID 33805602, 2021). "In another study, PAMAM dendrimers conjugated with lactobionic acid (GAL) and PEG were used in order to deliver siRNA against astrocyte elevated gene-1 (AEG-1) to human hepatocellular carcinoma xenograft mice." (PMID 33805602, 2021).
hyperglycaemia (4 papers, 2016 to 2024). "While increasing VIP and GAL immunoreactivity, molecules showed neuroprotective and pro-inflammatory properties, confirming that hyperglycemia leads to inflammatory conditions and damages autonomic neuronal cells." (PMID 32192078, 2020). "Under hyperglycaemia conditions, we observed an increase in GAL expression within nNOS-containing cell bodies." (PMID 30987291, 2019). "GAL also affects glucose metabolism, and its downregulation may also result from hyperglycaemia and may be a specific contributor to diabetic neuropathy." (PMID 38933596, 2024).
neuroblastoma (4 papers, 2015 to 2022). Neuroblastoma (NB) is the most common solid, extracranial childhood tumor. "By contrast, GAL exerted an antiproliferative effect via GAL2R in the human neuroblastoma SH-SY5Y cell line." (PMID 35954419, 2022). "The coexistence of GAL and beta-amyloid peptide in dense core secretory vesicles has been reported in the human neuroblastoma IMR32 cell line; this finding suggests that both substances are involved in the regulation of brain functions." (PMID 35954419, 2022). "It is important to note that the galaninergic system (by autocrine/paracrine mechanisms) exerts an anticancer action or a proliferative effect on neuroblastoma tumor cells; these effects are mediated by different GALRs, which induce different signaling pathways after the binding of GAL." (PMID 35954419, 2022). "Thus, neuroblastoma appears in very young children (median age: 17 months; 10.2 cases/million children under 15 years); GAL and GAL mRNA have been detected in this disease." (PMID 35954419, 2022). "Thus, GAL promoted the growth and development of human neuroblastoma in an autocrine/paracrine manner, and in the rat B104 neuroblastoma cell line, the peptide also increased the proliferation of tumor cells." (PMID 35954419, 2022). "In neuroblastoma, GAL might act as an autocrine/paracrine modulator and counteract neuronal differentiation." (PMID 35751103, 2022). "Moreover, GAL may function as an autocrine/paracrine modulator to influence tumor cell growth and development in neuroblastoma." (PMID 25504183, 2015). "The four UHR-NB upregulated genes (ADAM22, GAL, KLHL13 and TWIST1) were all upregulated in MYCN amplified neuroblastoma in 5 additional cohorts." (PMID 32629858, 2020).
Salmonella Infections (4 papers, 2016 to 2021). Infections with bacteria of the genus SALMONELLA. "However, in both Salmonella infection and Rhesus rotavirus infection, GAL treatment increased fluid secretion." (PMID 33552060, 2020).
seminoma (4 papers, 2015 to 2022). A radiosensitive malignant germ cell tumor found in the testis (especially undescended), and extragonadal sites (anterior mediastinum and pineal gland). "Among them, GDF3, NODAL, LEFTY1 /2, GAL, DPPA3, SOX2, DNMT3B /L, DPPA5, BCAT1, FGF2, PRDM14, ZIC3 and FZD7, while seminoma markers SOX17, cKIT and PRAME were downregulated." (PMID 26226633, 2015). "Expression of typical seminoma markers (PRDM1/BLIMP1, SOX17, PRAME, TFAP2C) was also detectable in TCam-2-ΔSOX2/FOXA2 tumor tissues, in contrast to EC reprogramming factors (GDF3, DPPA3, DNMT3B, GAL), which could only be detected in 2102EP in vivo or reprogrammed TCam-2 cells." (PMID 31130628, 2019). "We stratified the TCGA dataset of 156 samples into a seminoma expression signature (SOX17, PRAME, PRDM1 positive; SOX2, DNMT3B, GAL negative) and an EC expression signature (SOX2, DNMT3B, GAL positive; SOX17, PRAME, PRDM1 negative)." (PMID 32418994, 2020). "However, this current study could not observe signs of a seminoma‐to‐EC‐transition, since putative driver genes (NODAL, DNMT3B, DPPA3, and GAL) were rather downregulated upon co‐culture of TCam‐2 cells with TM components compared with TCam‐2 mono‐cultures." (PMID 35811571, 2022).
Stroke (4 papers, 2017 to 2025). Sudden impairment of blood flow to a part of the brain due to occlusion or rupture of an artery to the brain. "GAL’s ability to protect the neural system during injuries suggests that it has the potential to be used in stroke treatment." (PMID 28203483, 2017). "In this study, the intraluminal MCAO mouse model was performed to determine the effects that GAL would have on the outcome of stroke." (PMID 28203483, 2017).